VSTM4 (V-set and transmembrane domain containing 4)
Description:
Peptide Lv enhances L-type voltage-gated calcium channel (L-VGCC) currents in retinal photoreceptors.
Synonyms: C10orf72; FLJ31737
Tractability: Antibody: UniProt places it where antibodies can reach, with high confidence; UniProt predicts a signal peptide or a membrane-spanning region; its Gene Ontology location is reachable by antibodies, with medium confidence.
Gene: Protein-coding gene on chromosome 10 (49,014,236 to 49,115,522, reverse strand). Ensembl gene ENSG00000165633.
Subcellular location: Secreted (Peptide Lv); Cell membrane
Subcellular location (Human Protein Atlas): Nucleoplasm; Vesicles; Predicted to be secreted
Gene Ontology:
Molecular function: protein binding
Cellular component: extracellular region; membrane; plasma membrane
Genetic constraint (gnomAD): Loss-of-function variants: 14 observed, 30.44 expected, observed/expected ratio (o/e) 0.46, 90% interval 0.3 to 0.72. The upper end of that interval is the gene's LOEUF score, 0.72, which puts it in group 2 of 6, group 1 being the genes least tolerant of losing a copy. Missense variants: 332 observed, 346.13 expected, observed/expected ratio (o/e) 0.96, 90% interval 0.88 to 1.05. Synonymous variants: 147 observed, 148.2 expected, observed/expected ratio (o/e) 0.99, 90% interval 0.87 to 1.14.
Homologues: Orthologues: macaque VSTM4 (97% identical), chimpanzee VSTM4 (96% identical), mouse Vstm4 (88% identical), guinea pig VSTM4 (86% identical), rat Vstm4 (85% identical), dog VSTM4 (79% identical), pig VSTM4 (79% identical), rabbit VSTM4 (69% identical), zebrafish vstm4a (46% identical), zebrafish vstm4b (45% identical), tropical clawed frog vstm4 (43% identical). Paralogues in human: CD101 (20% identical), IGSF3 (20% identical), PTGFRN (18% identical), IGSF8 (15% identical), VSTM2A (6% identical).
Diseases named in the same sentence as VSTM4 in open-access papers:
VSTM4 is named in the same sentence as 7 diseases in open-access papers, as found by Europe PMC text mining. Sharing a sentence is not in itself a finding about the gene and the disease. The quoted sentences say what the papers report.
adenomyosis (1 paper, 2022). The growth of endometrial tissue inside the muscular wall of the uterine corpus. "Similarly, the PGR-repressed genes Gadd45a, Ets2, Vstm4 and C1qtnf6 may be important genes related to progesterone resistance-mediated mechanisms of adenomyosis development." (PMID 35563206, 2022).
asthma (1 paper, 2022). "Given that VSTM4 reduces IFN-γ and IL-2 produced by T cells and inhibits naïve CD4+T cell differentiation into Th1 cells, VSTM4 may contribute to a relative predominance of Th2 inflammation over Th1 inflammation in asthma." (PMID 36076228, 2022).
breast carcinoma (1 paper, 2024). "In breast cancer, short hairpin RNA screening and sequencing for tamoxifen resistance or sensitivity in patients with ER+ breast cancer patients revealed that the downregulation of VSTM4 can augment the sensitivity to tamoxifen treatment." (PMID 38728245, 2024).
colon cancer (1 paper, 2024). "Furthermore, high levels of VSTM4 have been noted in the tumors of murine models of colon cancer and melanoma." (PMID 38728245, 2024).
cancer (2 papers, 2023). A tumor composed of atypical neoplastic, often pleomorphic cells that invade other tissues. "Moreover, the PT complex upregulated the expression of specific potential cancer suppressor genes, such as cyclin G2, V-set and transmembrane domain containing 4 (VSTM4), coiled-coil domain containing 149 (CCDC149), CD2 molecule, and cyclin G2." (PMID 38027033, 2023). "Regarding the remaining model genes, like VSTM4 and VWA5A, they have also been reported to have connections with cancer." (PMID 38007443, 2023).
tumor (2 papers, 2021 to 2023). "The ectopic expression of VSTM4, another target of hsa-mir-153-5p, could impair the anti-tumor immunity with robust T cell inhibitory activity." (PMID 33926391, 2021).
VSTM4 also shares sentences with these, for which no sentence is quoted: melanoma (1 paper).